RIC8B (RIC8 guanine nucleotide exchange factor B)
Description:
Chaperone that specifically binds and folds nascent G(s) G-alpha proteins (GNAS and GNAL) prior to G protein heterotrimer formation, promoting their association with the plasma membrane (By similarity). Also acts as a guanine nucleotide exchange factor (GEF) for G(s) proteins by stimulating exchange of bound GDP for free GTP (By similarity). Acts as an important component for odorant signal transduction by mediating GNAL (G(olf)-alpha) folding, thereby promoting-dependent cAMP accumulation in olfactory sensory neurons (By similarity).
Synonyms: hSyn; FLJ10620; RIC8
Tractability: Antibody: its Gene Ontology location is reachable by antibodies, with high confidence. PROTAC: ubiquitination databases record sites on it; its protein half-life has been measured.
Gene: Protein-coding gene on chromosome 12 (106,774,621 to 106,889,316, forward strand). Ensembl gene ENSG00000111785.
Subcellular location: Cytoplasm, cell cortex
Subcellular location (Human Protein Atlas): Cytosol; Plasma membrane
Gene Ontology:
Molecular function: G-protein alpha-subunit binding; guanyl-nucleotide exchange factor activity; protein folding chaperone
Biological process: regulation of G protein-coupled receptor signaling pathway; G protein-coupled receptor signaling pathway; sensory perception of smell; protein folding
Cellular component: cytosol; plasma membrane; cytoplasm; cell cortex
Genetic constraint (gnomAD): Loss-of-function variants: 11 observed, 42.7 expected, observed/expected ratio (o/e) 0.26, 90% interval 0.16 to 0.43. The upper end of that interval is the gene's LOEUF score, 0.43, which puts it in group 1 of 6, group 1 being the genes least tolerant of losing a copy. Missense variants: 414 observed, 587.62 expected, observed/expected ratio (o/e) 0.7, 90% interval 0.65 to 0.76. Synonymous variants: 191 observed, 228.19 expected, observed/expected ratio (o/e) 0.84, 90% interval 0.74 to 0.94.
Homologues: Orthologues: chimpanzee RIC8B (100% identical), macaque RIC8B (100% identical), pig RIC8B (99% identical), dog RIC8B (99% identical), rabbit RIC8B (98% identical), mouse Ric8b (97% identical), rat Ric8b (96% identical), guinea pig RIC8B (95% identical), tropical clawed frog ric8b (69% identical), zebrafish ric8b (51% identical), Drosophila melanogaster ric8a (31% identical), Caenorhabditis elegans ric-8 (24% identical). Paralogues in human: RIC8A (47% identical).
Diseases named in the same sentence as RIC8B in open-access papers:
RIC8B is named in the same sentence as 30 diseases in open-access papers, as found by Europe PMC text mining. Sharing a sentence is not in itself a finding about the gene and the disease. The quoted sentences say what the papers report.
Encephalopathy (1 paper, 2024). Encephalopathy is a term that means brain disease, damage, or malfunction. "Altogether, the strength of the neomorphic Ric8B interaction provides the best predictive value for the clinical manifestations of GNAO1 encephalopathy mutations." (PMID 38874642, 2024). "Here, through a massive characterization of GNAO1 mutations, we uncovered a neomorphic feature shared by all Gαo encephalopathy mutants: a strong gain of interaction with Ric8A and, even more surprisingly, with Ric8B." (PMID 38874642, 2024). "As the strength of Gαo-Ric8B interactions correlates with disease severity, our study further identifies an efficient biomarker and predictor for clinical manifestations in GNAO1 encephalopathies." (PMID 38874642, 2024).
hepatoma (1 paper, 2020). "We knocked down Ric-8B in the HepG2 cell line (a human hepatoma cell line) and analyzed Akt (Ser473) phosphorylation in these cells." (PMID 32392211, 2020).
RIC8B also shares sentences with these, for which no sentence is quoted: infection (17 papers); viral infection (9); Anxiety (8); Obesity (5); depression (4); cognitive deficits (3); autism (2); epilepsy (2); Glucose intolerance (2); Insulin resistance (2); neuroblastoma (2); Stroke (2); alcohol addiction (1); allergic contact dermatitis (1); amyloid (1); atopic dermatitis (1); encephalitis (1); Headache (1); hematoma (1); ischemia (1); ischemic stroke (1); memory impairment (1); metabolic disorders (1); migraine (1); neurological disorders (1); psoriasis (1); spinal cord injury (1); synucleinopathies (1).